CASP8 (caspase 8)
Diseases named in the same sentence as CASP8 in open-access papers (continued):
Sharing a sentence is not in itself a finding about the gene and the disease.
melanoma (continued). "Still, much as for the protein-coding change caused by rs3769823, we cannot rule out a role for altered CASP8 splicing contributing to melanoma risk." (PMID 41542517, 2026). "In conclusion, ING4 may play an anti-tumor role in melanomas through the Fas/caspase-8 apoptosis pathway, including inhibiting melanoma cell proliferation and growth and inducing apoptosis." (PMID 39329914, 2024). "Casp8 induces PD-L1 ubiquitination and promotes its degradation by upregulating TNFAIP3 (A20) expression in murine melanoma, suggesting that reduced Casp8 expression may serve as a potential biomarker for predicting sensitivity to anti-PD-L1 immunotherapies." (PMID 38654302, 2024). "Additionally, the potential of CASP8 as a therapeutic target in other cancers, such as liver cancer, lung cancer, melanoma, and leukemia, has been explored, highlighting its broader applicability in cancer treatment." (PMID 39351539, 2024). "The inhibition of caspase-8 or caspase-10 (as well as disabling caspase-8) significantly reduces the efficacy of treatment, suggesting that this downstream pathway may play an important role in the response of melanoma cells to combination therapy." (PMID 39329914, 2024). "One notable observation we made was that the lead variant at the CASP8 locus (rs3769818) was associated with melanoma (G allele) but not with melanoma-linked phenotypes, such as tanning or naevus count." (PMID 35357426, 2022). "Knockdown of Casp8 in melanoma cells accelerates tumor growth in an immune‐dependent manner." (PMID 33934451, 2021). "This is consistent with SPARC activation of an MMP which could in turn cleave and inactivate an as yet unidentified death receptor ligand that is responsible for the caspase-8 activity observed after treatment of melanoma cells with MSA." (PMID 23470450, 2013). "Furthermore delNS1 viruses induced activation of caspase 9 and to a minor extent caspase 8, suggesting that both, intrinsic and extrinsic apoptotic pathways are triggered in infected melanoma cells." (PMID 22563505, 2012). "Indeed, gene expression correlation analyses suggest, for example, that E4F1 may play a prominent role for CASP8 regulation in melanocytes, while the activator IRF2 may play a larger role in regulation of CASP8 in melanomas." (PMID 41542517, 2026). "Functional polymorphisms in CASP8 and CASP10 may also influence melanoma susceptibility." (PMID 39329914, 2024). "-ING4 may play an anti-tumor role in melanomas through the Fas/caspase-8 apoptosis pathway." (PMID 39329914, 2024). "However, further studies are needed to investigate whether the elevated plasma CASP8 and BID are associated with an exacerbated apoptosis of peripheral blood mononuclear cells (PBMC) among these patients, similarly as in the case of melanoma patients." (PMID 37228491, 2023). "Importantly, we were also able to extend our analysis of germline alleles in melanoma patients to identify candidate functional variants at loci including MTAP/CDKN2A, where risk alleles were associated with phenotypes such as naevus count, and CASP8." (PMID 35357426, 2022). "While caspase-8 mutations occur most commonly in HNSCC (10%), they have also been reported in multiple other malignancies, including uterine (9.8%), stomach (4.8%), cervical (4.4%), colorectal (3.5%), melanoma (3.4%), and bladder (3.2%) cancers (TCGA, PanCancer Atlas)." (PMID 34362880, 2021). "Therefore, we further examined whether inhibition of caspase-8 could block USP5 cleavage in A375 melanoma cells." (PMID 31645897, 2019). "Moreover, to determine whether SFN-induced apoptosis in melanoma cells is caspase-dependent, caspase-8, caspase-9 and caspase-3 expression was assessed." (PMID 28864908, 2018). "In vitro, DM-1 also induced apoptosis via the extrinsic pathway by TNF-R1 and cleaved caspase-8 increase and by the intrinsic pathway via Bcl-2/Bax ratio decrease, cytochrome-c release and the electric mitochondrial membrane potential decrease in melanoma cells." (PMID 25742310, 2015).
melanoma (continued). "Inhibition of either caspase-8 or caspase-10 (as well as caspase-8 knockdown) significantly reduces treatment efficacy suggesting that this downstream pathway may play an important role in the response of melanoma cells to the combination treatment." (PMID 19684859, 2009). "In TCGA melanomas, we observed an FDR-significant eQTL for FLACC1 (P = 6.57 × 10−4), as well marginal eQTLs for CASP8 (P = 6.82 × 10−3) and TRAK2 (P = 0.03)." (PMID 41542517, 2026). "Another study found that TNF-α and IFN-γ were able to induce PANoptosis in 13 different human cancer cell lines from colon, lung, melanoma, and leukemia, through the activation of GSDMD, GSDME, caspase-8, caspase-3, caspase-7 and MLKL." (PMID 38877579, 2024). "We have characterized a TLR3-dependent pathway of apoptosis induction in melanoma cells that requires the adapter TRIF and uses similar signalling to TNF-R1, involving the activation of caspase-8 controlled by cIAP1/2." (PMID 35044632, 2022). "This loss of cFLIPL protein is a likely candidate for the increase in caspase-8-activation and apoptosis in Usp27xL-overexpressing and TNF- or pIC-treated melanoma cells tested here." (PMID 35044632, 2022). "In malignant melanoma cells, VPA was shown to enhance IFN-β-induced caspase 8 expression, thus improving its response to TMZ treatment." (PMID 34660288, 2021). "In order to characterize the apoptotic cell signaling pathway induced by PCV2 ORF3, activation of initiator caspase-8 and effector caspase-3 were examined in ORF3-transfected B16F10 mouse melanoma cells and WT mice primary splenocytes." (PMID 30526524, 2018). "Because activation of caspase-8 was evident, we investigated the expression of death receptors and their ligands in BSE-treated A375 melanoma cells." (PMID 25072850, 2014). "The A375 melanoma cells initiated extrinsic apoptosis at 24 hours post hypericin-PDT, evident by the activation of the initiator CASP8 and executioner CASP3." (PMID 25076130, 2014). "Caspase-8 and -3 are the major initiator and effector caspase, respectively, in TRAIL-induced apoptosis of melanoma cells, whereas the mitochondrial apoptotic pathway is known to play an important role in TRAIL-induced apoptosis of melanoma." (PMID 20003459, 2009). "As was observed for melanoma cells, IFNγ treatment of Ptpn2 knockout CT26 and MC38 cells enhanced the expression of the IFNγ response genes Cxcl1, Ccl5, Stat1, Stat2, Stat3, Irf1, Pd-l1, Tap1, and Casp8, compared with IFNγ-treated control cells." (PMID 36968224, 2023). "A promising strategy to inhibit melanoma progression has been found for the combination of DM-1, a curcumin analog, and dacarbazine in B16F10 melanoma-bearing mice by the activation of apoptosis with the cleavage of caspase-3, caspase-8, and caspase-9." (PMID 36829966, 2023). "TRAIL resistance may also be accounted for by the downregulation of initiator caspase-8 and 10 as reported in a study of acquired resistance to TRAIL in melanoma." (PMID 34299249, 2021). "Taken together, the interplay of caspases-3, XIAP and Bcl-2 family members, initiated by non-limiting amounts of TRAIL receptors and caspase-8, appears to play a central role in melanoma cell death upon exposure to IZI1551/Birinapant." (PMID 32081986, 2020). "Our previous study showed that CTPG induced apoptosis in melanoma B16-F10 cells by mitochondria-dependent pathway that increased the level of cleaved caspase-9 but not caspase-8." (PMID 30314494, 2018).
melanoma (continued). "Previously, it was reported that MFH-induced decrease in the viability of melanoma and non-melanoma skin cancer cells results from necrosis and endoplasmic reticulum-mediated apoptosis, since activation of caspase 3/7, but no caspase 8 or 9 has been observed." (PMID 27229857, 2016). "Significantly, no PARP cleavage was found in the A375 melanoma cells but both CASP8 and CASP3 were cleaved at 24 hours suggesting that perhaps the PARP cleavage occurs at a later, delayed time-point that fell outside the scope of this study." (PMID 25076130, 2014). "In this study, caspase-8, which plays an important role in the activation of the extrinsic apoptosis pathway, did not increase after exposing the melanoma cells to zeaxanthin." (PMID 24223611, 2013). "We show that in melanoma cell lines, which are typically resistant to chemotherapeutic agents, XIAP knock-down sensitises cells to TRAIL treatment in vitro, also favouring the accumulation of cleaved caspase-8." (PMID 20461078, 2010). "Altogether, these findings show that Bortezomib sensitises melanoma lines to TRAIL without affecting the caspase-8 levels." (PMID 20461078, 2010). "Having found that 2-DG enhances TRAIL-induced activation of caspase-8, we examined whether it regulates the cell surface expression of TRAIL receptors in melanoma cells." (PMID 20003459, 2009). "Given the dramatic caspase-8 and Bid cleavage observed following treatment with Mcl-1 DsiRNA and ABT-737 in melanoma, we investigated whether expression of either protein correlates with combination treatment response." (PMID 19684859, 2009). "Of the remaining variants, rs3769821 was significant only in a joint analysis of data from both melanoma and HEK293T kidney cells (PMPRA v.1 = 3.11 × 10−4) with direction of effect matching that observed in individual luciferase assays (reverse orientation) and consistent with the CASP8 eQTL." (PMID 41542517, 2026). "Flavonoid 15, a non-studied till now compound, induced caspase-8 activation in A375 melanoma cells." (PMID 38339241, 2024). "Enhanced processing of major effector caspases (caspase-3, caspase-7, caspase-8 and caspase-9) to their active forms and cleavage of PARP (a target of activated effector caspases) was observed at 48 hours following treatment of the BRAF V600E mutant (A375) human melanoma cell line with ixazomib." (PMID 27783987, 2016). "Enhanced processing of the major effector caspases (caspase-3, caspase-7, caspase-8 and caspase-9) to their active forms and cleavage of PARP (a target of activated effector caspases) was observed at 48 hours following treatment of the A375 human melanoma cells with ixazomib and bortezomib." (PMID 27783987, 2016). "However, we did not observe substantial activation of caspase 8/9 suggesting that TP-472 treatment might be activating caspase 8/9-independent apoptotic pathways in melanoma cells." (PMID 34771678, 2021). "However, since TP-472 treatment did not substantially activate caspase 8/9, we anticipate that induction of apoptosis in the treated melanoma cells might involve caspase 8/9-independent apoptotic pathways." (PMID 34771678, 2021). "It is noteworthy that none of the melanoma models studied lacked TRAIL-R1/R2 or caspase-8 expression, and TRAIL-Rs or caspase-8 amounts did not appear crucial to predict responsiveness." (PMID 32081986, 2020). "No sign of caspase-8 or caspase-9 activation, but the cleavage of caspase 7 were seen upon CPT treatment in suspended melanoma." (PMID 28977882, 2017). "By contrast, in melanoma IRAK-M–mediated apoptosis occurred independent of caspase-9 and caspase-8." (PMID 32533049, 2020).
neuroblastoma (99 papers, 2002 to 2025). Neuroblastoma (NB) is the most common solid, extracranial childhood tumor. "Apart from its proteolytic role in apoptosis, caspase-8 promotes adhesion and Erk signaling in neuroblastoma cells via recruiting PM-associated Src tyrosine kinase." (PMID 37971931, 2024). "To exclude potential cleavage of caspase-2 by caspase-8, which can undergo p62-mediated activation, we used SK-N-BE cells, a neuroblastoma cell line characterized by loss of caspase-8 expression." (PMID 39543123, 2024). "Interaction was performed in a caspase 8 deficient neuroblastoma cell line, which originally derived from a metastatic bone tumor biopsy and as a sub-line of the parental line SK-N-SH." (PMID 36832063, 2023). "In this study, they established an immunocompetent mouse model for metastatic neuroblastoma which recapitulated not only overexpression of MYCN but also loss of Caspase-8 expression." (PMID 37274289, 2023). "In this regard, Caspase-8 expression has been reported to be downregulated through promoter methylation in some tumors, including neuroblastoma, and mutated in some others." (PMID 37444381, 2023). "Low Caspase-8 levels are associated with a worse prognosis in patients with neuroblastoma, neuroendocrine lung tumors and gynecological tumors, in which Caspase-8 loss promotes tumor aggressiveness and invasiveness." (PMID 37444381, 2023). "The suppression of caspase-8 expression potentiates neuroblastoma metastases, and reconstitution of caspase-8 in deficient neuroblastoma cells suppressed their metastases." (PMID 33810241, 2021). "The loss of caspase-8 expression occurs very frequently in neuroendocrine cancers such as neuroblastoma, medulloblastoma, and glioblastoma." (PMID 33026575, 2021). "In neuroblastoma cells, anoikis obtained by unligated integrin-induced caspase 8 activation prevents metastasis and the caspase-8 suppression is associated with increased invasive capacity in vivo." (PMID 32727075, 2020). "Another target of IRF1 and IRF2 that is implicated in neuroblastoma is Caspase-8 and its family member Caspase-7." (PMID 31178872, 2019). "Deregulation of the caspase-8 expression associated with CASP8 gene promoter hypermethylation has been described in neuroblastoma, retinoblastoma (Rb), von Hippel-Lindau, and sporadic phaeochromocytoma cells." (PMID 31248188, 2019). "Further, loss of Casp8 expression is associated with human neuroblastomas with N-Myc amplification, small-cell lung carcinoma, and relapsed glioblastoma multiforme." (PMID 30598363, 2019). "This resulted in the loss or reduced expression of caspase-8, an effector caspase, which mediates the downstream death signaling, and further rendering neuroblastoma resistant to TRAIL-induced apoptosis." (PMID 31652776, 2019). "Loss of caspase-8 mRNA/protein expression has been demonstrated in high grade small cell lung cancers, neuroendocrine lung cancers and paediatric neuroblastoma." (PMID 27798717, 2017). "Second, we validated this finding in a cellular context using transfected neuroblastoma cell lines deficient in caspase-8." (PMID 27109099, 2016). "Contrarily, the presence of the -652 6N Del or the CASP8 302His variant was reported to be an unfavorable prognostic factor in colorectal cancer or neuroblastoma." (PMID 27507139, 2016). "Our findings provide an epigenetic explanation to a previous study wherein loss of CASP8 protein expression was observed in a majority of neuroblastomas." (PMID 22984959, 2012). "A long-standing dilemma in neuroblastoma research is the proposed association between CASP8 methylation and MYCN amplification." (PMID 22984959, 2012).
neuroblastoma (continued). "We show that the neuroblastoma NB7 cells are deficient in caspase-8 yet express death receptors DR4 and DR5 and caspases -3 (an effector caspase) and -10 (an apical caspase)." (PMID 20967281, 2010). "Loss of caspase-8 gene expression by gene silencing has been reported to occur in neuroblastoma, medulloblastoma, and small cell lung carcinoma (SCLC)." (PMID 24281211, 2010). "In neuroblastoma, a loss of caspase-8 prevented apoptosis by integrin-mediated cell death and therefore promoted metastasis." (PMID 20808443, 2010). "Absence or down-regulation of CASP8 could cause resistance to apoptosis and is correlated with unfavorable disease outcomes, such as childhood medulloblastoma and neuroblastoma." (PMID 38081857, 2023). "Bcl-2 overexpression inhibited TRAIL-induced Bax activation, loss of MOMP, and cleavage of caspase-8 into p43/p41 and p18 active fragments, cleavage of Bid, and processing of the caspase-3 p20 fragment into the p17/p12 active fragments in SH-EP neuroblastoma cells." (PMID 37065863, 2023). "Furthermore, caspase-8-deficient neuroblastoma cells are known to be resistant to apoptosis mediated by death receptors and by doxorubicin." (PMID 34832966, 2021). "Since high-grade Neuroblastoma, which are largely therapy resistant, are often characterized by Caspase-8 deficiency, we aimed to investigate whether TLR3 can induce an alternative programmed cell death pathway in the absence of Caspase-8." (PMID 34011952, 2021). "Restoration of CASP8 expression in deficient neuroblastoma cells suppressed their metastases." (PMID 33381579, 2020). "Similarly, methylation of the caspase 8 gene (CASP8), which encodes a cysteine protease regulated in a death-receptor-dependent and independent manner, was found in neuroblastomas and other tumors." (PMID 29649096, 2018). "However, caspase-8 deficiency in a mouse neuroblastoma model led to a significant increase in metastases, due to ECM structural changes and production of inflammatory cytokines such as TGF-β." (PMID 29854765, 2018). "Compared to these results, the ability of DHS to induce caspase-8 independent apoptosis in the IMR32 cells may have clinical implications, given that loss of caspase-8 expression was reported in many patients, bearing malignant neuroblastomas." (PMID 29088756, 2017). "Moreover, a significant fraction of aggressive stage IV neuroblastoma cells (10–30%) maintain caspase-8 expression, and inactivation mutations are surprisingly rare." (PMID 27101103, 2016). "Loss of caspase-8 has been associated with metastasis in neuroblastoma." (PMID 20808443, 2010). "Therefore, we next used caspase-8-deficient neuroblastoma cells to evaluate the role of caspase-8 DEDs in tumor progression." (PMID 19924290, 2009). "Methylation of the CASP8 gene has been associated with low levels of caspase-8 expression, reduced response to chemotherapeutic agents and poor outcome in a number of different cancer types including medulloblastoma and neuroblastoma, although this remains controversial at least in neuroblastoma." (PMID 25157404, 2014). "For instance, in a molecular analysis, methylation-specific PCR of the genes FLIP, TSP1, DcR1, DcR2, DR4, DR5, CASP8 and HIC1 was implemented on 20 neuroblastomas, 23 VHL-associated pheochromocytomas and 16 sporadic pheochromocytomas." (PMID 40558831, 2025). "(2009) reported increased caspase 8 levels in a neuroblastoma cell line following etoposide treatment." (PMID 40995510, 2025). "As an autophagosome regulator, the depletion of chmp2a triggers a caspase-8 cascade, inducing apoptosis in osteosarcoma and neuroblastoma cells." (PMID 39456653, 2024).